SIRT1 (sirtuin 1)
Diseases named in the same sentence as SIRT1 in open-access papers (continued):
Sharing a sentence is not in itself a finding about the gene and the disease.
glioblastoma (36 papers, 2011 to 2025). The most malignant astrocytic tumor (WHO grade IV). "SIRT1 was proposed to be affirmatively linked with cell viability, proliferative ability and growth of U87 glioblastoma cells." (PMID 38597418, 2024). "Taken together, these findings suggest that Oxamate selectively suppresses glioblastoma proliferation—accompanied by reduced Sirt1 expression and senescence induction—while having minimal impact on normal astrocytes." (PMID 40565174, 2025). "Research indicates that UA increases the expression levels of SIRT1 and FOXO1 in glioblastoma cells, with SIRT1 playing a crucial role in mediating UA’s effects." (PMID 40710366, 2025). "In this study, we identified a dose‐dependent diminish in SIRT1 levels, exhibiting the ability of irradiated riboflavin suppressing C6 glioblastoma cells proliferation through SIRT1 signalling." (PMID 38597418, 2024). "Overexpression of SIRT1 has been associated with the malignant transformation of several cancer subtypes, while oral cancer and glioblastoma cells exhibit minimal expression of SIRT1." (PMID 37949849, 2023). "Moreover, the high expression level of SIRT1 was associated with a better survival rate in glioblastoma patients, and SIRT1 overexpression could enhance the inhibitory effect of Urolithin A on the tumor growth and metastasis of glioblastoma." (PMID 35252011, 2022). "Some studies have shown an increase in the level of SIRT1 in various tumors such as hepatocellular carcinoma, breast, prostate, ovarian, gastric, and colon cancer, leukemia, melanoma, lymphoma, and glioblastoma." (PMID 34942940, 2021). "Activators of SIRT1 have been evaluated in preclinical studies and were shown to be a promising therapeutic strategy for glioblastoma and multiple myeloma." (PMID 32051395, 2020). "In the present study, we examined the function and characteristics of SRT2183 (a Sirt1 stimulator) in several glioblastoma cells." (PMID 31319814, 2019). "This study will provide a novel approach for cancer therapies, especially glioblastoma, and SIRT1 activators inducing autophagy/mitophagy will be potentially of great value as a novel leading drug for future cancer therapeutics." (PMID 29991742, 2018). "To further demonstrate that SIRT1 is downregulated in brain cancer, we applied three TMA containing 70 samples of glioblastoma and 35 samples of normal brain tissues to evaluate the expression of SIRT1." (PMID 29991742, 2018). "Together, these results indicate that SIRT1 is downregulated in brain cancer, especially in glioblastoma." (PMID 29991742, 2018). "Immunohistochemical analyses demonstrated decreased expression of SIRT1 in glioblastoma samples compared with normal brain tissues (P < 0.0001)." (PMID 29991742, 2018). "SIRT1 is also consistently upregulated in malignant cells or tissues from patients with glioblastoma, and prostate, colorectal, or skin cancer." (PMID 26091232, 2015). "At the same time, SIRT1 exerts opposite anti-cancer effects in glioblastoma of the nervous system." (PMID 40292294, 2025). "A study identified Comp 5 (small-molecule compound F0911–7667) as an effective and selective activator of SIRT1, which induces autophagic cell death in glioblastoma cells via the AMPK-mTOR-ULK (AMP-activated protein kinase–mammalian target of rapamycin–Unc-51-like kinase) complex pathway." (PMID 40710366, 2025). "A significant increase in the level of SIRT1 was revealed in glioblastoma." (PMID 34942940, 2021). "SIRT1, as a negative regulator, has been implicated in the modulation of PI3K/Akt pathway by deacetylation of the tumor suppressor PTEN and down-regulation of both Akt and phosphorylation levels to inhibit the PI3K/Akt pathway in glioblastoma cells." (PMID 30622543, 2018).
glioblastoma (continued). "Similarly, the benzopyran-based compound 18 inhibits SIRT1/2 activities and acts as a cytostatic agent in glioblastoma cells, whereas the dual SIRT1/2 inhibitor tenovin-1 induces apoptosis in sarcoma cells." (PMID 29401749, 2018). "Clinically, Rios and colleagues described a case of a glioblastoma patient treated with AMD3100 (plerixafor) and a combination of a mammalian target of rapamycin (mTOR), a Sirtuin-1 (Sirt1), and an EGFRvIII inhibitor after conventional chemo-radiotherapy." (PMID 36980182, 2023). "Moreover, we showed that Comp 5 had a therapeutic potential on glioblastoma (GBM) and induced autophagy/mitophagy by activating SIRT1 in vivo." (PMID 29991742, 2018). "Since we evidenced in glioblastomas that the amounts of CD44 are high and that the amount of SIRT1 that inactivates EP300 is low, we can assume that this situation may facilitate activation of STAT3 by acetylation." (PMID 21655185, 2011). "Interestingly, SIRT6, together with SIRT1, coordinated the switch from glucose to FAO during the acute inflammatory response, and transcriptional activation of SIRT6 via FOXO3a inhibited the Warburg effect in glioblastoma cells." (PMID 31849939, 2019).
Myocardial fibrosis (32 papers, 2014 to 2025). "The amelioration of cardiac function and myocardial fibrosis was associated with an activation of silence information regulator 1 (Sirt1) which can directly combine with Smad3 and promote its deacetylation." (PMID 35081907, 2022). "This suggests that resistance exercise inhibits MI myocardial fibrosis by promoting irisin expression through the activation of the AMP-activated protein kinase (AMPK)-SIRT1 pathway." (PMID 40182630, 2025). "Mechanistically, it inhibited NLRP3 inflammasome activation by upregulating SIRT1 expression, thereby reducing cardiac inflammatory infiltration, myocardial fibrosis, and cardiomyocyte apoptosis, ultimately mitigating DOX-induced cardiac injury." (PMID 39925805, 2025). "Four weeks of aerobic exercise (60 min/day, 4 weeks) improved mitochondrial biogenesis and myocardial fibrosis by activating the Sirt1/PGC-1 α/PI3K/Akt signaling pathway and alleviated myocardial fibrosis in infarcted mice." (PMID 39796197, 2025). "Our findings confirm the involvement of the Sirt1/γ-H2AX pathway in the myocardial fibrosis observed in PF mice." (PMID 40297134, 2025). "In preclinical HFpEF models, antagomiRs against miR-34a and miR-21 reduce endothelial senescence and myocardial fibrosis, respectively, by derepressing SIRT1 and PTEN pathways." (PMID 40862748, 2025). "The AMPK/SIRT1 pathway mediates myocardial fibrosis, cardiac remodeling, and systolic dysfunction in aging, and is involved in reducing myocardial I/R injury and reducing diabetic myocardial microvascular injury." (PMID 38172692, 2024). "The results showed that mir-217 negatively regulated SIRT1 and aggravated the myocardial fibrosis induced by TGF-β1 via NLRP3 inflammasome activation." (PMID 38561456, 2024). "The mir-217 mimics offset this effect of GAS5 on myocardial fibrosis, pyroptosis and SIRT1, and the mir-217 inhibitor enhanced all these effects of GAS5." (PMID 38561456, 2024). "In cardiovascular diseases, SIRT1 has been shown to protect against cardiomyocyte apoptosis, maintain endothelial function, and attenuate myocardial fibrosis through a variety of pathways." (PMID 38017499, 2023). "It has been found that SIRT1 inhibits cardiomyocyte apoptosis, protects endothelial function, and alleviates myocardial fibrosis through a variety of pathways." (PMID 38017499, 2023). "RSV effectively ameliorated myocardial fibrosis and improved cardiac function by regulating Sirt1/Smad3 deacetylation pathway in rat model with DCM." (PMID 35081907, 2022). "Rresveratrol effectively ameliorated myocardial fibrosis and improved cardiac function by regulating Sirt1/Smad3 deacetylation pathway in the rat model with dilated cardiomyopathy." (PMID 35081907, 2022). "It was found that the cardiac dysfunction and myocardial fibrosis induced by doxorubicin were significantly improved by acacetin in mice with impaired Nrf2/HO‐1 and Sirt1/pAMPK molecules, which is reversed by acacetin treatment." (PMID 32918384, 2020). "Based on previous studies and relevant experiments, we found that SIRT1 is closely related to myocardial fibrosis." (PMID 32350389, 2020). "While our experiment was being conducted, several papers related to SIRT1 and myocardial fibrosis were published." (PMID 32350389, 2020). "Collectively, these data demonstrated that BAK displayed its protective properties against myocardial fibrosis and collagen deposition in diabetic myocardium via SIRT1 signaling." (PMID 33062139, 2020). "Accordingly, this study aimed at delineating a role for SIRT-1 in mediating L-ARG protection against streptozotocin (STZ) induced myocardial fibrosis." (PMID 25501750, 2014).
Myocardial fibrosis (continued). "SIRT1 has been shown to exert a potent cardioprotective effect in cardiovascular disorders, and thus, pharmacological stimulation of SIRT1 may act as a novel therapeutic strategy to prevent myocardial fibrosis." (PMID 40343296, 2025). "Consequently, they influence DNA methylation and miRNA profiles related to oxidative stress and myocardial fibrosis, influencing the activity of SIRT1, Nrf2, and other transcriptional regulators." (PMID 41515210, 2025). "In this study, we demonstrated that DEL‐1 could alleviate myocardial fibrosis, inflammation, and cardiomyocyte apoptosis in MI in vitro and in vivo via regulating the Sirt1/NF‐κB signaling pathway." (PMID 41146562, 2025). "Our findings revealed that DEL‐1 could alleviate myocardial fibrosis, inflammation, and cardiomyocyte apoptosis induced by MI via regulating the sirtuin 1 (Sirt1)/nuclear factor‐kappaB (NF‐κB) signaling pathway." (PMID 41146562, 2025). "Resveratrol reversed BMSCs senescence and enhanced their transplantation efficacy in diabetic myocardial infarction rats by downregulating miR-34a and activating SIRT1, as manifested by improved cardiac function, reduced myocardial fibrosis, and increased angiogenesis." (PMID 41584283, 2025). "SAL protects against myocardial fibrosis infused by Ang II by activating the SIRT1-Nrf2 pathway." (PMID 40343296, 2025). "We hypothesized that swimming (a form of aerobic exercise) may alleviate myocardial fibrosis in diabetic rats by inducing irisin through activating miR-34a-mediated SIRT1/PGC-1α/FNDC5 signal pathway." (PMID 39250437, 2024). "Up-regulation of AMPK and SIRT1 may be a potential therapeutic strategy to improve aging-related myocardial fibrosis and cardiac remodeling." (PMID 38172692, 2024). "And mir-217 could down-regulate the expression of SIRT1 then aggravate myocardial fibrosis induced by NLRP3 inflammasome activation-mediated pyroptosis in vitro." (PMID 38561456, 2024). "Interestingly, Sirt1 suppression in the heart tissue impeded the efficacy of resveratrol in inhibiting myocardial fibrosis and enhancing long‐term cardiac function." (PMID 37487007, 2023). "The in vivo study showed that XFC could inhibit apoptosis, promote angiogenesis and improve myocardial fibrosis through SIRT1." (PMID 36760468, 2023). "Particularly, resveratrol results in improving adriamycin-induced myocardial fibrosis by increasing SIRT1 and by decreasing factor β1 (TGFβ1), which lead to an increase of glutathione (GSH) and SOD and a decrease of MDA, Hyp, TNF-α and creatine kinase-MB (CK-MB)." (PMID 36615832, 2022). "In addition, we demonstrated that DEL‐1 could alleviate myocardial fibrosis, inflammation, and cardiomyocyte apoptosis in MI via regulating the Sirt1/NF‐κB signaling pathway." (PMID 41146562, 2025). "Therefore, we investigated whether DEL‐1 overexpression alleviated myocardial fibrosis, inflammation, and cardiomyocyte apoptosis in MI through regulating the Sirt1/NF‐κB pathway." (PMID 41146562, 2025). "Therefore we hypothesized that GAS5 could regulate the downstream target gene SIRT1 via mir-217 and subsequently inhibit myocardial fibrosis." (PMID 38561456, 2024). "Also, it can promote the repair of diabetic myocardial ischemic injury by up-regulating the levels of Sirt1 and eNOS, increasing NO bioavailability, preserving endothelial function, improving neovascularization, and inhibiting myocardial fibrosis and myocardial apoptosis." (PMID 38179501, 2023). "XFC could inhibit apoptosis, promote angiogenesis, and improve myocardial fibrosis through SIRT1." (PMID 36760468, 2023). "Moreover, as resveratrol activates SIRT1, it could interfere with myocardial fibrosis through the factor β (TGF-β)/Smad2/3 pathway, eliminating collagen synthesis and cardiac fibroblast differentiation." (PMID 36615832, 2022).
Myocardial fibrosis (continued). "Thus Sirt1/Smad3 deacetylation pathway may also be involved in the development of myocardial fibrosis." (PMID 35081907, 2022). "It achieved its anti-inflammatory and antioxidant effects by regulating the SIRT1/NF-κB/NLRP3 inflammasome signaling pathway, thereby reducing myocardial fibrosis and hypertrophy." (PMID 39925805, 2025). "Gallic acid and urolithin A are examples of microbial-derived polyphenolic metabolites that control miRNA expression and DNA methylation, promoting SIRT1/PGC-1α-mediated pathways and preventing myocardial fibrosis." (PMID 41515210, 2025). "Our results showed that DAPA inhibits EndMT and improves myocardial fibrosis in non-diabetic mice by activating SIRT1 and promoting its regulation of NICD deacetylation." (PMID 38017499, 2023). "Since small animals are prone to heart failure and cardiac dysfunction after modelling, long-term feeding is difficult; thus, there is a lack of long-term observational studies on SIRT1 and myocardial fibrosis simulating the clinical disease process." (PMID 32350389, 2020). "The findings of this study demonstrated that the activated SIRT1-mediated regulation of NICD deacetylation is indispensable for the inhibitory effects of DAPA on EndMT and myocardial fibrosis in non-diabetic mice." (PMID 38017499, 2023).
fibrosis (31 papers, 2019 to 2026). the formation of excess fibrous connective tissue in an organ or tissue in a reparative or reactive process. "SIRT1 activator SRT1720 restores the expression and activity of SIRT1 in diabetic mice and renal TECs subjected to high glucose-induced fibrosis models." (PMID 39335456, 2024). "The probable mechanism is that SIRT1 can regulate intestinal fibrosis and can protect the intestinal mucosal barrier function to participate in the process of post-necrotizing enterocolitis stricture." (PMID 35958178, 2022). "Various genes which are potentially regulated by this miRNA are involved in calcium and potassium handling in myocytes (CACNB2, KCNN3), in protection of cells against oxidative stress (SIRT1), and in regulating cardiac fibrosis (STAT3)." (PMID 35052352, 2021). "In summary, SIRT1 activation rescued the disrupted endothelial barrier and decreased cardiac fibrosis formation in mice with endothelial cell-specific CRIF1 deletion." (PMID 33430144, 2021). "We demonstrated for the first time that in a CCl4-treated mouse fibrosis model, PKCδ is a key player in modulating NF-κB via SIRT1 signaling." (PMID 31533364, 2019). "The effects of NMN on hypoxia-associated adipose fibrosis, inflammation, NAD+/SIRT1 axis alteration, and HIF-1α activation were evaluated by real-time polymerase chain reaction (PCR), western blots, immunohistochemistry staining, immunoprecipitation, and assay kits." (PMID 36777361, 2023). "On the other hand, the low expression of SIRT1 lost the ability to curb NF-κB p65 so that the activation of NF-κB signaling pathway enhanced the occurrence of inflammatory response and intestinal fibrosis, and elevated the transition of NEC from the acute phase to the chronic phase." (PMID 35958178, 2022). "Similarly, research carried out in a NAFLD‐derived fibrosis model reported that melatonin restored Sirtuin1 (SIRT1) levels, protein responsible for regulating longevity and cellular metabolism, by inhibiting miR‐34a‐5p expression." (PMID 35404472, 2022). "EX‐527, as a SIRT1‐selective inhibitor, relieve hepatic fibrosis by up‐regulating SIRT4 expression." (PMID 34272822, 2021). "In the present study, we explored whether the PKCδ signaling in inflammatory fibrosis is involved in the regulation of SIRT1 expression and the regulation of α-Smooth muscle actin (α-SMA) expression through NF-κB." (PMID 31533364, 2019). "Taken together, the downregulation of SIRT1 during liver fibrosis could induce a series of cellular impairments and alterations in liver microenvironment, which substantially contribute to the progression toward cirrhosis and markedly increase the risk of HCC development." (PMID 41281762, 2025). "In the physiological aging process in mice, 12-week NAC treatment ameliorated aortic fibrosis possibly by stimulating M2 macrophage polarization, and SIRT1, SIRT3 and FOXO1 may play a role in unidentified pathways linking vascular oxidative stress to fibrosis associated with aging." (PMID 34530696, 2021). "Therefore, SIRT1 might be a therapeutic target for preventing cardiac fibrosis induced by MR." (PMID 32350389, 2020). "However, pharmacological intervention using SIRT1 and NRF2 activator resveratrol improved renal function, proteinuria, glomerulosclerosis, tubular fibrosis, and inflammation in aged kidneys." (PMID 36899375, 2023). "Resveratrol could exert protection against DOX-induced cardiotoxicity via activating SIRT1 and AMPK signaling cascades thus mitigating oxidative stress, mitochondrial injury, cardiomyocyte apoptosis and cardiac fibrosis induced by DOX exposure." (PMID 31733141, 2019).
amyotrophic lateral sclerosis (30 papers, 2009 to 2025). Amyotrophic lateral sclerosis (ALS) is a neurodegenerative disease characterized by progressive muscular paralysis reflecting degeneration of motor neurons in the primary motor cortex, corticospinal tracts, brainstem and spinal cord. "Overexpression of SIRT1 even extended the lifespan of mice with amyotrophic lateral sclerosis (ALS) associated with SOD1 mutation." (PMID 41502422, 2025). "SIRT1 plays a critical role in mitigating damages caused by aging and a number of neurodegenerative diseases including amyotrophic lateral sclerosis (ALS)." (PMID 30295421, 2018). "Resveratrol, a SIRT1 activator, reportedly protects the amyotrophic lateral sclerosis (ALS) cell model from mutant superoxide dismutase 1 (SOD1)-mediated toxicity by up-regulation of SIRT1 expression." (PMID 33737560, 2021). "It has been shown that RSV ameliorates motor neuron degeneration and improves survival mainly through increasing the expression of SIRT1 in the SOD1G93A mouse model of amyotrophic lateral sclerosis." (PMID 29081884, 2017). "SIRT1 alleviates animal and cellular models of amyotrophic lateral sclerosis (ALS), Huntington’s disease, Alzheimer’s disease, and an α-synuclein model of PD9." (PMID 26167274, 2015). "Recently, SIRT1 has been implicated in the pathologic process in lumbar segment of the spinal cord in a SOD1G93A transgenic mouse model of amyotrophic lateral sclerosis, suggesting that SIRT1 may play some role in pain modulation." (PMID 24959710, 2014). "The participation of silent mating type information regulation 2 homolog 1 (SIRT1) in amyotrophic lateral sclerosis (ALS) has been reported in many studies." (PMID 35448021, 2022). "However, it remains unknown if SIRT1 also acts to prevent pathological changes that accrue in motor neurons during aging and amyotrophic lateral sclerosis (ALS)." (PMID 30295421, 2018).